ABHD13 (abhydrolase domain containing 13)
Synonyms: C13orf6; bA153I24.2; FLJ14906; BEM46L1
Tractability: Antibody: UniProt predicts a signal peptide or a membrane-spanning region. PROTAC: ubiquitination databases record sites on it; its protein half-life has been measured.
Gene: Protein-coding gene on chromosome 13 (108,218,167 to 108,234,243, forward strand). Ensembl gene ENSG00000139826.
Subcellular location: Membrane
Subcellular location (Human Protein Atlas): Cytosol
Gene Ontology:
Molecular function: palmitoyl-(protein) hydrolase activity
Biological process: macromolecule depalmitoylation
Cellular component: membrane; cytoplasm; dendrite cytoplasm
Genetic constraint (gnomAD): Loss-of-function variants: 7 observed, 26.09 expected, observed/expected ratio (o/e) 0.27, 90% interval 0.15 to 0.5. The upper end of that interval is the gene's LOEUF score, 0.5, which puts it in group 2 of 6, group 1 being the genes least tolerant of losing a copy. Missense variants: 302 observed, 424.39 expected, observed/expected ratio (o/e) 0.71, 90% interval 0.65 to 0.78. Synonymous variants: 133 observed, 143.3 expected, observed/expected ratio (o/e) 0.93, 90% interval 0.81 to 1.07.
Homologues: Orthologues: chimpanzee ABHD13 (100% identical), macaque ABHD13 (100% identical), dog ABHD13 (99% identical), pig ABHD13 (99% identical), rabbit ABHD13 (98% identical), guinea pig ABHD13 (96% identical), mouse Abhd13 (96% identical), rat Abhd13 (96% identical), tropical clawed frog abhd13 (88% identical), zebrafish abhd13 (79% identical), Drosophila melanogaster Bem46 (40% identical), Caenorhabditis elegans F01D5.7 (12% identical), and 1 more. Paralogues in human: ABHD12B (23% identical), ABHD12 (22% identical), ABHD17C (18% identical), ABHD17A (17% identical), ABHD17B (17% identical), ABHD16A (15% identical), ABHD16B (13% identical).
Diseases named in the same sentence as ABHD13 in open-access papers:
ABHD13 is named in the same sentence as 2 diseases in open-access papers, as found by Europe PMC text mining. Sharing a sentence is not in itself a finding about the gene and the disease. The quoted sentences say what the papers report.
mental deficiency (1 paper, 2025). "Among the detected genes on ECA17, ABHD13 is related to the rare Williams syndrome in humans that cause growth delay, short stature, mental deficiency and some facial features developing with age." (PMID 39754479, 2025).
ABHD13 also shares sentences with these, for which no sentence is quoted: Williams syndrome (1 paper).